IL6 (interleukin 6)
Diseases named in the same sentence as IL6 in open-access papers (continued):
Sharing a sentence is not in itself a finding about the gene and the disease.
colitis (continued). "We next tested the functional role of IL-6 during the induction of colitis in dnKO mice." (PMID 25478789, 2014). "Investigation of the production of IL-1β and IL-6 in colitis mice serum confirmed our results." (PMID 24504372, 2014). "The therapeutic effects of heat-killed VSL#3 on colitis may due to its effects on IL-6/STAT3 pathway." (PMID 24451125, 2013). "Studies in animal models of trinitro-benzene-sulfonic acid-induced colitis and concanavalin A (Con A)-induced hepatitis indicated that the blockade of IL-17A by IL-17R: FC is dependent primarily on the downregulation of IL-6 and TNF-α." (PMID 23977238, 2013). "Recent reports have shown that the neutralization of IL-17 using IL-17 receptor Ad:FC downregulates the expression of IL-6, tumor necrosis factor, etc., in colitis induced by trinitro-benzene-sulfonic acid, in atherosclerosis and in concanavalin A-induced hepatitis." (PMID 23977238, 2013). "Thus, reduction of IL-6 alone in the colon is insufficient to confer protection against the clinical signs of colitis unless it is accompanied by a substantial reduction in the infiltration of the colon by activated macrophages." (PMID 23469045, 2013). "During DSS-induced colitis NF-κB-regulated cytokines like IL-6 or TNFα are massively activated." (PMID 23977205, 2013). "Our findings that L-Arg also effectively reduced other proinflammatory mediators, such as the innate immune cell products IL-1α, IL-1β, and IL-6, as well as the prototype Th17 cytokine, IL-17, suggest that it may be broadly beneficial in colitis." (PMID 22428068, 2012). "We investigated the role of IL-6 in S100A9 expression in CECs using a colitis model." (PMID 22962574, 2012). "Liver responses detected in infected animals at 3 DPI overlapped many targets associated with acute colitis and disease severity including MCP-1, MIP-1α, MIP-1β, RANTES, and KC and neutrophil/Th17-related targets such as KC, IL-1β, IL-6, IL-12/23p40, and G-CSF." (PMID 22427959, 2012). "Of important, IL-6 production was also increased in DSS-induced colitis." (PMID 22962574, 2012). "The infiltration of GR-1+ cells and histopathology of colon tissue were consistently and notably reduced when S100A9 expression was down-regulated, suggesting that the recruitment of immune cells in the colonic epithelium results from IL-6-induced S100A9 expression in CECs in DSS-induced colitis." (PMID 22962574, 2012). "IL-6 had a similar up-regulating effect in early DSS colitis." (PMID 22675442, 2012). "Elevated S100A9 expression in CECs mediated by an IL-6/STAT3 signaling cascade may play an important role in the development of colitis." (PMID 22962574, 2012). "Our lab has previously documented that deletion of the IL-6 gene from the hemizygous dnTGFβRII mice significantly improved colitis as indicated by substantially reduced intestinal lymphocytic infiltration, reduced diarrhea and increased body weight, while maintaining the autoimmune cholangitis." (PMID 23145171, 2012). "The first is that severe shigellosis (i.e. hemolytic uremic syndrome, thrombocytopenia and severe colitis >1 week) is associated with elevated IL-6 rather than TNF-α." (PMID 22887873, 2012). "Using the AOM + DSS model, Hyun and colleagues showed that IL-17A-deficient mice developed a less severe colitis than wild-type mice, as demonstrated by the decreased cell infiltrate and the diminished expression of pro-inflammatory factors (e.g., TNF-α, IL-6)." (PMID 23109839, 2012). "When used to treat colonic inflammation induced by TNBS administration to Balb/c mice, ciprofloxacin effectively protected against development of local signs of colitis and markedly reduced local generation of inflammatory mediators including IL-1β, IL-6, IFNγ and TNFα." (PMID 22046243, 2011).
colitis (continued). "Rosmarinus officinalis L. oil, mainly constituted by 1,8-cineole along with α-pinene, camphor and p-cymene was only able to reduce the pro-inflammatory IL-6 production in the mouse colon in which colitis was induced by 2,4,6-trinitrobenzene sulphonic acid (TNBS), not suppressing IL-1β." (PMID 21160452, 2010). "Like IL-4, IL-6 has been demonstrated to induce Th2 differentiation via direct action on Th cells, while it was also required for the development of Th1 immunity in murine tuberculosis, colitis and experimental autoimmune encephalomyelitis." (PMID 20442861, 2010). "The anti-inflammatory effects of diverse combination of thyme (p-cymene and thymol as main components) and oregano (carvacrol as major component) oils on mice with TNBS-induced colitis showed that some combinations lowered the amounts of IL-1β and IL-6 cytokines." (PMID 21160452, 2010). "B. vulgatus mpk mono-colonized mice only showed expression of IL-6 mRNA, whereas E. coli mpk mono-colonized mice, prone to develop colitis and SPF IL-2−/−-mice already suffering from colitis, revealed high levels of IL-1α, IL-1β, TNF-α, IFN-γ, IL-10 and IL-6 mRNA in the intestine." (PMID 18545662, 2008). "The absence of colitis in B. vulgatus mpk mono-colonized IL-2−/−-mice was associated with an enhanced production of IL-6 and a decreased production of TNF-α in LP DC as compared to E. coli mpk mono-colonized mice." (PMID 18545662, 2008). "The absence of colitis in B. vulgatus mpk mono-colonized IL-2−/− mice was associated with an increased expression of only IL-6 mRNA in the intestinal tissue." (PMID 18545662, 2008). "Taken together these data suggest that B. vulgatus mpk induced IL-6 might account at least partially for the immune-regulatory function of B. vulgatus mpk and the prevention of colitis in B. vulgatus mpk mono-colonized IL-2−/−-mice." (PMID 18545662, 2008). "As well, WT(PFKFB3fl/flLyz2-Cre) mice developed less severe colitis compared to WT(PFKFB3fl/fl) groups, showing reduced weight loss, lower DAI scores, longer colon length, diminished histopathology and intestinal damage, and lower inflammatory cytokine levels of Il1β, Il6, and Tnfα." (PMID 41378888, 2026). "Treatment with the selective TAAR1 antagonist EPPTB substantially improved colitis symptoms, including reduced weight loss, lower DAI scores, prevention of colon shortening, diminished tissue damage, and decreased expression of pro-inflammatory cytokines (TNF-α, IL-6, and IL-1β) in colonic tissue." (PMID 41550498, 2026). "Based on human UC biopsy sample examination and an animal model of colitis (induced by dextran sulfate sodium - DSS in CHGA gene knockout mice), a positive correlation between CgA and M1 macrophage-associated pro-inflammatory cytokines such as IL-1β, IL-6, and TNF have been observed." (PMID 40370467, 2025). "In a study based on mice models of colitis and colitis-associated cancer (CAC), necrostatin-1 significantly suppressed colitis symptoms in mice, including weight loss, colon shortening, colonic mucosa damage and its severity, and the excessive production of interleukin-6." (PMID 41303584, 2025). "Moreover, the results of network pharmacology have validated existing literature and our experimental findings, thereby confirming the TRPM8 signaling pathway and inflammatory factors such as TNF-α, IFN-γ, and IL-6 as pivotal components in the regulatory role exerted by COP on DSS-induced colitis." (PMID 40053041, 2025). "Hence, to further dissect the protective effect of the combined treatment of vitamin C/allicin on DSS-induced colitis in mice, we quantified the relative gene expression levels of inflammation-related cytokines IL-1β, IL-6, and TNF-α in the middle and posterior segments of the colon." (PMID 40077487, 2025).
colitis (continued). "Our findings show that Cyn significantly alleviates TNBS-induced colitis symptoms in mice, as evidenced by reduced body weight loss, colon shortening, DAI score, colon histopathology score, and lower levels of inflammatory factors (IL-1β, TNF-α, and IL-6) compared to the model group." (PMID 39902073, 2024). "To verify our hypothesis that IA-0130 suppresses the excessive expression of pro-inflammatory cytokines, we analyzed the mRNA and protein expression of pro-inflammatory cytokines, TNF-α, IL-1β, IL-6, and IL-17A, which are important in colitis development and maintenance." (PMID 38916850, 2024). "This, in turn, has an impact on the integrity of the intestinal barrier and the stability of the intestinal microenvironment, and that blocking the IL-6 -STAT3 signaling pathway through CN-encapsulated probiotics could prevent colitis-related colorectal cancer." (PMID 38717677, 2024). "In addition, RT-qPCR and the ELISA assay demonstrated that the pro-inflammatory cytokines of TNF-α, IL-1β, and IL-6 increased in number in the colitis tissues and sera, whereas UTI could reverse this pro-inflammatory phenotype." (PMID 38397811, 2024). "In DSS-induced colitis, specifically, immunocyte dysfunction leads to abnormal secretion levels of pro-inflammatory cytokines such as tumor necrosis factor-alpha, interleukin-1β, and IL-6, while anti-inflammatory cytokines like IL-10 secretion decrease (p < 0.01)." (PMID 38612465, 2024). "In addition, during the acute phase of colitis caused by DSS, serum from C57BL/6J mice exhibits a cytokine expression pattern characterized by TNF-α, IFN-γ, and IL-6 from M1 macrophages/Th1 cells and IL-17 from Th17 cells similar to the expression pattern found in colon." (PMID 39176394, 2024). "Therefore, regulation of the excessive IL-6 signaling cascade is important for treating colitis." (PMID 38916850, 2024). "We hypothesized that the inhibitory effect of IA-0130 on DSS-induced colitis symptoms and abnormal expression of inflammatory cytokines and TJ proteins may occur as a result of IA-0130 regulating the excessive activation of the IL-6 signaling pathway." (PMID 38916850, 2024). "In a dextran sodium sulfate (DSS)-induced murine colitis model, mice with oral stigmasterol administration had a delayed onset of colitis, a reduced pathohistological score in the colon; and a downregulated expression of inflammatory factors, including IL-6, IL-1β, and TNF-α." (PMID 37685017, 2023). "Furthermore, exogenous quercetin suppressed the pro-inflammatory immune responses in murine DSS and acetic acid-induced colitis, as indicated by inhibited colonic recruitment of neutrophils and T lymphocytes and decreased IL-6 concentration in DSS colitis mice, further supporting our presented data." (PMID 37896170, 2023). "In addition to being associated with colitis, fatty liver, gout, etc., it is also positively correlated with levels of inflammatory markers (TNF-α, IL-1β, and IL-6)." (PMID 38032532, 2023). "Our results showed that DSS-induced acute colitis led to impaired autophagy flux in IECs, and that administration of oat beta-glucan could promote autophagy flux in IECs, downregulate the expressions of IL-1β, IL-6 and TNF-α and reduce intestinal inflammation." (PMID 37441529, 2023). "Besides, FMT rescued the elevated inflammatory factors TNF-α, IL-6, and IL-1β in serum and colonic tissue of mice colitis model, indicating that both of CA- and EA-altered microbiota can effectively transfer the colitis protection." (PMID 37813835, 2023). "The S. verbenaca-treated group showed a marked downregulation in the mRNA expression of Il-1β, Il-6, Il-12a and Il-23 (p < 0.05 vs. colitic control group), thus confirming the amelioration in the colonic inflammatory status exerted by the extract in this experimental model of colitis." (PMID 38136191, 2023).
colitis (continued). "They showed that it could reduce MDA, NO, MPO, hydroxyproline, TNF-α, IL-1β, IL-6, iNOs mRNA, COX-2 mRNA, IFN-γ mRNA, Bcl-2-associated X protein (Bax), Caspase-1, NF-kB and IκBα and increase IL-10, SOD and GSH in an in vivo model of TNBS-induced colitis." (PMID 36677021, 2023). "Finally, we found that insulin alleviated colonic inflammation, as exemplified by the declines in the levels of inflammatory cytokines such as GM-CSF and IL-6 in the plasma of mice with DSS-induced colitis, and GM-CSF is a factor that induces macrophage differentiation and survival." (PMID 37491256, 2023). "After induction of colitis by DSS, there was weight loss, diarrhea, fecal bleeding, increased mortality, ulcers, loss of colon, and inflammation configured by cellular infiltration, the elevation of pro-inflammatory cytokines (IL-1β, IL-18, TNF-α, and IL-6) and NO." (PMID 36677021, 2023). "Compared with the CT group, a colitis model was successfully constructed in the DSS group, as evidenced by higher weight loss, an increased DAI, shorter colon length, more serious colonic tissue damage, and higher levels of pro-inflammatory cytokines (IL-6, IL-1β, TNF-α, and IL-1α)." (PMID 37505716, 2023). "In addition, extracts of Rubia cordifolia and L. riboside, as novel prebiotics, have been shown to alleviate the symptoms of colitis in DSS mice by inhibiting the IL-6/JAK2/STAT3 inflammatory pathway and NLRP3 inflammatory vesicles, restoring Th1/Th2 and Th17/Treg balance, among other mechanisms." (PMID 37389342, 2023). "Furthermore, MLKL attenuated colon inflammation and colitis tumorigenesis via suppression of inflammatory responses, inhibited intestinal tumorigenesis by suppressing the IL-6/JAK2/STAT3 pathway and promoted cellular differentiation in myeloid leukemia by facilitating the release of G-CSF." (PMID 36828808, 2023). "Since we found increased expression of costimulatory molecules and IL-6 levels in colitic PTENΔDC mice, we asked whether ablation of the microbiota or of IL-6R signaling rescues the high mortality observed in PTENΔDC mice during colitis." (PMID 35514976, 2022). "This was dependent on distinct intestinal inflammatory conditions, and the experimental model analyzed, which could explain why Paclik and coauthors in a wild-type colitis model demonstrated that galectin-4 reduced the secretion of IL-6 as well as TNF-α, CXCL8, IL-10, by activated T cells." (PMID 36139125, 2022). "While CD40/TNFRS5 is one of the TNF-α receptors involved in colitis associated to IL-1β production, no significant variation was found in TNFα, IL-6, and adiponectin expression levels between HL-ARA and HL + ARA groups compared with the mice fed the Std-ARA diet." (PMID 36558497, 2022). "Notch signaling activated the production of the pro-inflammatory cytokine IL-6 via the NF-kB pathway in colonic epithelium, and the blockade of the Notch pathway resulted in a reduction of intestinal inflammation in a model of trinitrobenzene sulfonic acid-induced colitis in mice." (PMID 36422542, 2022). "In this same study, IL-6 originating in the dam contributed to expansion of Th17 cell populations in the gut of the offspring that were responsible for the enhanced resistance to subsequent bacterial infection but also enhanced sensitivity to colitis in the offspring later in life." (PMID 35381031, 2022). "However, Bp8 intervention slightly reduced the colonic IL-6 levels in colitis mice, which may be attributed to the individual differences in mice and the strain differences in B. pseudolongum." (PMID 35681301, 2022). "Also, the alteration of gut microbiota from P. tenera extract effectively alleviated colitis symptoms such as body weight loss, colon length loss, and diarrhea, and also attenuated the mRNA expression of pro-inflammatory cytokines (TNF-α, IL-6, IL-1β, and COX-2)." (PMID 35877732, 2022).
colitis (continued). "Similarly, IL-6 positive cells were increased following DSS induction of colitis, these cells were also dispersed throughout the mucosa and submucosa and their levels were greatly reduced after treatment with BA or BANPs, and the best reduction was also achieved in the BANPs receiving group." (PMID 35332200, 2022). "Importantly we see evidence of upregulation of TNF-α, IL-1β, and IL-6 in various brain regions of colitis models, which may be sourced from or interact with neurons, microglia, and other cells." (PMID 34983592, 2022). "Interestingly, also memantine acting by blocking N-methyl-D-aspartate (NMDA) receptors significantly attenuates macroscopic and microscopic signs of colitis in a mouse model decreasing the plasma levels of interleukin-1β, interleukin-6, and colon level of tumor necrosis factor-α and myeloperoxidase." (PMID 34797427, 2022). "Furthermore, treatment with NK151, NK173, NK175, or their (3:1:1) mix suppressed IS-induced colitis: they suppressed colonic IL-1β and IL-6 expression and the NF-κB+CD11c+ cell number along with the fecal endotoxin level, meanwhile increasing the IL-10 cytokine level in the colon." (PMID 35631220, 2022). "To further verify our hypothesis that activation of P2RY13 may promote the development of colitis through the IL-6/STAT3 signaling pathway, we generated intestinal epithelial cells STAT3 conditional knockout (STAT3△IEC) mouse strain as described in the Materials and Methods." (PMID 35982893, 2022). "To determine whether the dosing time-dependent anti-colitis effects of CR in mice are associated with berberine and REV-ERBα, we measured colonic MDA and MPO activities as well as IL-1β and IL-6 levels in Rev-erbα−/− mice with colitis after 7 days’ CR treatment." (PMID 34393786, 2021). "The decrease in Dicer expression could increase the levels of cytosolic DNA and IL-6 mRNA under oxidative stress in inflammatory bowel tissues, while berberine alleviates colitis by recovering Dicer expression to exert a preventive effect on colitis-associated tumorigenesis." (PMID 35046810, 2021). "We demonstrated that olaparib improved TNBS-induced colitis in mice, reduced histological damage of the colon, diminished the number and length of the ulcers, inhibited proinflammatory cytokine production (IL-1β, IL-6), but it enhanced the level of anti-inflammatory cytokine IL-10." (PMID 34567413, 2021). "JUG reversed the DSS-induced up-regulation of proinflammatory cytokines, including interleukin (IL)-6, 12, 21, and 23, and tumor necrosis factor-alpha, and anti-inflammatory cytokines, such as IL-10 and transforming growth factor-beta, in the serum of the colitis mice." (PMID 34421890, 2021). "The BTWD has been found to also alleviate inflammation in the mouse model of colitis, which may be related to a variety of signaling pathways, including the modulation of intestinal microflora and inflammatory signaling pathways, such as IL-6/STAT3." (PMID 34539797, 2021). "Colitis can cause intestinal epithelial barrier dysfunction and increase its permeability; furthermore, antigens can enter the intestinal lumen, causing the accumulation of lymphocytes and macrophages and resulting in the release of inflammatory factors and cytokines, such as TNF-α, IL-6, and IL-1β." (PMID 31936300, 2020). "Previous study has shown that inhibiting or blocking the activation of IL-6/STAT3 signaling pathway can attenuate the colon injury and inflammation in DSS-induced colitis, and RNA-seq analysis also pointed out that the underlying mechanism may related with IL-6/STAT3 pathway." (PMID 32517784, 2020). "Furthermore, A. muciniphila-derived OMVs could attenuate the release of pro-inflammatory IL-6 from colon epithelial cells in vitro and decrease the severity of colitis in DSS-induced mouse model." (PMID 33281770, 2020).